HTR7P1 (5-hydroxytryptamine receptor 7 pseudogene 1)
Synonyms: formerly HTR7P
Gene: Transcribed processed pseudogene on chromosome 12 (13,001,499 to 13,002,834, forward strand). Ensembl gene ENSG00000183935.
Diseases named in the same sentence as HTR7P1 in open-access papers:
HTR7P1 is named in the same sentence as 4 diseases in open-access papers, as found by Europe PMC text mining. Sharing a sentence is not in itself a finding about the gene and the disease. The quoted sentences say what the papers report.
melanoma (1 paper, 2024). A malignant, usually aggressive tumor composed of atypical, neoplastic melanocytes. "For example, of the 16 total genes driving the association between melanoma and nevus count, only two (MTAP and ERVFRD‐3) were shared by all three tissues, and six (MAFF, HEBP1, HTR7P1, EMP1, GPRC5A, C9orf66) were specific to melanocyte." (PMID 38308491, 2024).
prostate carcinoma (1 paper, 2019). A carcinoma that arises from epithelial cells of the prostate gland. "We identified HTR7P1 pseudogene in the same PGG family as HTR7 gene, which is potentially regulated by hsa-miR-607 and hsa-miR-3654 in the TCGA prostate cancer dataset." (PMID 31029062, 2019).
HTR7P1 also shares sentences with these, for which no sentence is quoted: Ataxia (1 paper); nevus (1).